RNU6-335P (RNA, U6 small nuclear 335, pseudogene)
Gene: Small nuclear RNA gene on chromosome 4 (183,675,603 to 183,675,715, reverse strand). Ensembl gene ENSG00000201433.
Homologues: Orthologues: chimpanzee U6 (99% identical), macaque U6 (89% identical), pig U6 (72% identical), mouse Gm24593 (70% identical), rat LOC120101183 (69% identical), dog U6 (65% identical), mouse Gm55921 (50% identical). Paralogues in human: RNU6-1122P (81% identical), RNU6-1060P (80% identical), RNU6-15P (80% identical), RNU6-25P (80% identical), RNU6-33P (80% identical), RNU6-378P (80% identical), RNU6-43P (80% identical), RNU6-1 (79% identical), RNU6-11P (79% identical), RNU6-1243P (79% identical), RNU6-140P (79% identical), RNU6-2 (79% identical), and 1285 more.